FOXP3 (forkhead box P3)
Diseases named in the same sentence as FOXP3 in open-access papers (continued):
Sharing a sentence is not in itself a finding about the gene and the disease.
schistosomiasis (9 papers, 2007 to 2022). An infectious disease caused by parasitic trematodes of the genus Schistosoma that colonize human blood vessels and release eggs that can cause granulomatous reactions leading to acute (swimmer's itch or acute schistosomiasis syndrome) or chronic disease. "More experiments are clearly needed at this point to address the likelihood of such a contribution of ex-Foxp3 in the host protective Th2 response during experimental schistosomiasis." (PMID 30379806, 2018). "First, in an experimental murine model of schistosomiasis, we demonstrated that Foxp3+ Treg cells up-regulated IL-4Rα expression." (PMID 30379806, 2018). "Further analyses on the need for the host to up-regulate this receptor during schistosomiasis were then conducted using a murine model of specific deletion of IL-4Rα within the Foxp3+ Treg cell population, termed Foxp3cre IL-4Rα−/lox mice." (PMID 30379806, 2018). "We first investigated the level of activation of FOXP3+ Tregs in the blood of Schistosoma japonicum-infected patients with schistosomiasis of various degrees of severity." (PMID 26731721, 2016). "FOXP3+ Tregs could regulate inflammation, but it is unclear where these cells are produced and what roles they play in human schistosomiasis." (PMID 26731721, 2016). "Studies have shown that CD4+CD25+Foxp3+ Treg cells are induced mainly by egg antigens during the infection, and play an important suppressive role in down-modulating granulomatous response in schistosomiasis." (PMID 25604731, 2015). "Hence, it is possible that IL-4Rα up-regulation on Foxp3+ Treg cells during acute experimental schistosomiasis observed in our study could occur as an attempt for the host to rapidly mount a protective Th2 immune response during acute schistosomiasis." (PMID 30379806, 2018). "CXCR5+ follicular regulatory (Tfr) cells, an especially-classified thymic-derived Foxp3+ Tregs, are reported to increase within CD4+ T cells and total Tfh cells in schistosomiasis patients." (PMID 32894174, 2020).
Alzheimer disease (8 papers, 2012 to 2025). A progressive, neurodegenerative disease characterized by loss of function and death of nerve cells in several areas of the brain leading to loss of cognitive function such as memory and language. "Furthermore, oxidative damage leads to an increase in IL-6 production, which has been shown to inhibit Foxp3 expression in Treg differentiation, suggesting that oxidative stress is the cause of a decrease of Treg levels in patients with Alzheimer’s disease." (PMID 40078868, 2025). "According to this, blocking of IL-17A in a wild-type mouse model of lung Ad resulted in a decreased number of Foxp3+ Tregs and an increase of IFN-γ and TNF-α producing CD4+ T cells leading to a significant reduction of tumor growth." (PMID 22855687, 2012). "Moreover, blocking of IL-17A in a mouse model of lung Ad resulted in a decrease of Foxp3+ Treg numbers." (PMID 22855687, 2012).
cervical intraepithelial neoplasia (8 papers, 2014 to 2025). "Interestingly, FOXP3 can be expressed in some CC and cervical intraepithelial neoplasia (CIN) cases." (PMID 41007768, 2025).
Chagas disease (8 papers, 2011 to 2025). A parasitic infection caused by Trypanosoma cruzi. "In the case of Trypanosoma cruzi infection, specialized regulatory Foxp3+ T (Treg) cells suppress protective type-1 effector responses." (PMID 38683845, 2024). "Results show that indeed rSSP4 induced expansion of CD4+CD25+FOXP3+ T cells that exacerbate Chagas disease by promoting parasite proliferation during acute T. cruzi infection." (PMID 23509755, 2013). "One import result found in the present study was a positive correlation between IL-17 and Foxp3 expression in PBMC among Chagas' disease patients." (PMID 22545173, 2012). "Because we found that CD4+CD25+FOXP3+ T cells induced by immunization with rSSP4 promoted the development of Chagas disease, we wanted to see whether these regulatory T cells were antigen specific." (PMID 23509755, 2013). "However, the same authors reported later in a study that patients with the indeterminate form of Chagas' disease exhibited a higher frequency of CD4+CD25high T cell expressing Foxp3 and IL-10 as compared to those individuals with cardiomyopathy." (PMID 22545173, 2012). "Additionally, the presence of perforin-expressing CD4+ cytotoxic T-cells has shown an inverse relationship with LVEF, while an increase in Foxp3+high CD25+high CD4+ T-cells and IL-17 expression has been associated with a positive LVEF and improved cardiac function in human Chagas disease." (PMID 40391216, 2025). "Cardiac patients exhibited higher mRNA expression of IFN-γ, TNF-α and lower mRNA expression of IL-10, Foxp3, AHR, and GATA-3 than those with the indeterminate clinical form of Chagas disease." (PMID 27115869, 2016). "In agreement with previous data, increased levels of Foxp3+ CD25+ cells were also observed in the IND group after in vitro stimulation with T. cruzi antigens, emphasizing once again the role of Treg cells in the control of Chagas' disease morbidity." (PMID 21655351, 2011).
chorioamnionitis (8 papers, 2011 to 2025). A morphologic finding indicating inflammation of the fetal sac membranes. "We believe that these findings suggest that decreased Foxp3+ cells in the spleen in acute chorioamnionitis may be associated with a decreased T-regulatory component and concomitant upregulation of activated T-cells in the lung." (PMID 30473713, 2018). "FOXP3 expression was significantly reduced on T-regs isolated from infants born to mothers with chorioamnionitis." (PMID 32152273, 2020). "Lastly, it is known that IL-6 and TNF-alpha are increased in chorioamnionitis and these cytokines also result in methylation at the Foxp3 promoter, that then down regulates Treg cell development." (PMID 30473713, 2018). "Fetal splenic tissue showed significantly decreased Foxp3 staining (β: − 0.11, SD: 0.04, p = 0.01) in subjects with acute chorioamnionitis compared to controls." (PMID 30473713, 2018). "Similarly, those infants born to mothers with chorioamnionitis also exhibited significantly lower levels of FOXP3 expression in T-regs, suggesting reduced functionality." (PMID 32152273, 2020). "Moreover, we found that fetal tissue responses to histologic acute chorioamnionitis revealed a decreased percentage of splenic Foxp3+ cells in the stillbirth subjects." (PMID 30473713, 2018). "In our study, we found fewer Foxp3 cells in the spleen in infants with chorioamnionitis." (PMID 30473713, 2018). "Furthermore, suggestive evidence is provided that a disturbed balancebetween effector T-cells and FoxP3+ cells plays a role in ileal inflammationand subsequent mucosal damage in utero following chorioamnionitis." (PMID 21479249, 2011). "Similarly, RORγt/FOXP3 mRNA ratio is increased in the blood of premature infants exposed to severe chorioamnionitis, but not to mild chorioamnionitis." (PMID 32636848, 2020). "They found that at 1 week of life infants, with funisitis exposure and not chorioamnionitis exposure had increased RORC expression and RORC/FOXP3 ratio, which continued over the first 4 postnatal weeks." (PMID 30473713, 2018). "In the stillborn subjects with chorioamnionitis, we observed a decrease in splenic Foxp3+ cells and an increase in lung CD3+ cells compared with subjects that did not have chorioamnionitis." (PMID 30473713, 2018).
gastric adenocarcinoma (8 papers, 2013 to 2023). "For example, Helicobacter pylori infection, which is associated with gastric adenocarcinoma, also induces miR-155 expression in T cells, but via Foxp3." (PMID 23637592, 2013). "In our previous study, we concluded that the expression of the autophagy-related protein, Beclin-1, was associated with tumor FOXP3 expression and Tregs in gastric adenocarcinoma and that Beclin-1 expression acts as a favorable prognostic factor in gastric adenocarcinoma." (PMID 34414959, 2021). "SKP2 expression was positively correlated with the tumoral FOXP3 overexpression (P < .0001), Beclin-1 expression (P < .0001), and Treg infiltration (P = .031) in gastric adenocarcinoma." (PMID 34414959, 2021). "Correlation between SKP2 and tumoral FOXP3 expression and clinicopathological variables in 182 gastric adenocarcinomas." (PMID 34414959, 2021). "Based on these findings, we can infer that the increased oncogenic properties of SKP2 in gastric adenocarcinoma are repressed by an increased FOXP3 expression." (PMID 34414959, 2021). "The antioncogenic effect of Beclin-1 and FOXP3 expression in gastric adenocarcinoma is related to SKP2 expression." (PMID 34414959, 2021). "Our study showed a complex interrelationship among SKP2, Beclin-1, and FOXP3 expression (in the tumor cells and Tregs) in gastric adenocarcinoma." (PMID 34414959, 2021). "A positive tumoral FOXP3 expression was observed in 49.2% (90/182) of the gastric adenocarcinoma cases." (PMID 34414959, 2021). "In conclusion, the antioncogenic effect of Beclin-1 and FOXP3 expression in gastric adenocarcinoma is corresponding to SKP2 expression." (PMID 34414959, 2021). "In the present study, the expression of SKP2 and its relationship with Beclin-1 and FOXP3 expression in gastric adenocarcinoma were investigated." (PMID 34414959, 2021). "Our study showed a complex interrelationship between SKP2 and Beclin-1 and FOXP3 expression in gastric adenocarcinoma." (PMID 34414959, 2021). "In addition, SKP2 expression was correlated with the tumoral FOXP3 expression in gastric adenocarcinoma." (PMID 34414959, 2021). "Correlation among SKP2, tumoral FOXP3, Beclin-1, and Tregs in 182 gastric adenocarcinomas." (PMID 34414959, 2021). "Immunohistochemistry and automated image analysis was applied to assess the density of T lymphocytes (CD3+, CD8+, FoxP3+) and NK cells (NKp46+) in chemoradiotherapy-naïve tumors from a consecutive cohort of 174 patients with resected esophageal or gastric adenocarcinoma." (PMID 29069772, 2017).
hepatitis B (8 papers, 2011 to 2020). "Here, we present data describing an association between FOXP3 genetic variation and susceptibility to hepatitis B-related HCC in all donors." (PMID 23759077, 2013). "Our study aimed to evaluate the association between FOXP3 gene polymorphisms and hepatitis B-related HCC." (PMID 23759077, 2013). "Our results suggested that the FOXP3 gene polymorphisms at rs2280883 and rs3761549 may be associated with hepatitis B-related HCC." (PMID 23759077, 2013). "This phenomenon indicates that the FOXP3 gene may play a role in inflammation and chronic infections such as hepatitis B, which may increase the risk of carcinoma." (PMID 23759077, 2013). "Overall, our study showed that FOXP3 gene polymorphisms are related to hepatitis B-related HCC." (PMID 23759077, 2013). "However, it remains unclear whether FOXP3 gene polymorphism is associated with hepatitis B-related HCC." (PMID 23759077, 2013). "Because of the complex relationship between inflammation and a tumor and the important role of FOXP3 in this relationship, it is difficult to clearly describe the relevance between FOXP3 gene polymorphisms and CHB or hepatitis B-related HCC." (PMID 23759077, 2013). "In contrast, the frequency of CD39+FoxP3+ Treg cells was significantly negatively correlated with serum ALT in total hepatitis B patients (n = 39, r = 0.344, P = 0.012), and a strong correlation was also observed in CAH patients (r = 0.508, P = 0.019)." (PMID 22489829, 2012). "To further explore the role of Foxp3 in patients with hepatitis B, we collected the peripheral blood from 34 CHB patients and 30 ACLF patients, and then evaluated the expression of Foxp3 as detected by qPCR and FCM assays." (PMID 21489307, 2011). "To further value the role of Foxp3 in patients with hepatitis B, we detected the expression level of Foxp3 in liver tissue from patients infected by HBV by using qPCR and immunohistochemistry techniques." (PMID 21489307, 2011). "In addition, we observed that there were no marked differences in the frequencies of total FoxP3+ Tregs or CD39+FoxP3+ Tregs between hepatitis B patients with or without serum HBeAg expression." (PMID 22489829, 2012). "Using triple fluorescence staining, we confirmed that CD39 and FoxP3 expressions co-localized within regions with partial CD4+ T cells, indicating that the CD4+FoxP3+CD39+ Treg cells did exist in the portal area of liver tissue and might be involved in hepatitis B pathogenesis." (PMID 22489829, 2012).
Hypercholesterolemia (8 papers, 2016 to 2026). An increased concentration of cholesterol in the blood. "By this, hypercholesterolemia increased the development of FoxP3+ T cells in the thymus and elevated the FoxP3+ Treg cell population in the periphery." (PMID 29142309, 2017). "Hypercholesterolemia elevated the FoxP3 expression level and population size of peripheral Treg cells, but did not prevent enhanced proliferation of stimulated T cells." (PMID 29142309, 2017). "In conclusion, we found that hypercholesterolemia affects the homeostatic as well as the proliferative TCR stimulation and increases the thymic as well as the peripheral FoxP3+ Treg cell population." (PMID 29142309, 2017). "Despite the link between hypercholesterolemia and TCR stimulation and the importance of homeostatic TCR stimulation for Treg cells, the ability of hypercholesterolemia to affect FoxP3 expression and the Treg cell population has not been investigated so far." (PMID 29142309, 2017).
leishmaniasis (8 papers, 2011 to 2024). Infectious disease that is transmitted through the bite of hematophagous female phlebotomine sand flies. "In human leishmaniasis, elevated intra-lesional FoxP3 and IL-10 were associated with unresponsiveness to treatment during L. amazonensis infection." (PMID 26465878, 2015). "It is possible that that role of FoxP3 in leishmaniasis differs depending on not only the causal Leishmania species but also on the tissue studied and host species as demonstrated in this study." (PMID 26465878, 2015). "In other mouse strains and in studies of human leishmaniasis, however, both CD4+CD25−FoxP3− as well as CD4+CD25+FoxP3+ T cells have been implicated in the long-term control of infection and development of sterile immunity." (PMID 23825956, 2013). "In a non-healing mouse model of Leishmaniasis, high frequency of IL-10 producing regulatory T cells (CD4+CD25+FoxP3+) is observed at local site." (PMID 25032977, 2014).
lung squamous cell carcinoma (8 papers, 2020 to 2024). "This study investigated the prognostic significance of tumor-infiltrating Foxp3 + lymphocytes (Foxp3 + TILs) in squamous cell lung cancer (SQ-LC) objectively." (PMID 38402536, 2024). "Hence, in the present study, we investigated the prognostic significance of Foxp3 + TILs in a more objective way by focusing on squamous cell lung cancer (SQ-LC), which is often accompanied by inflammation in the TME." (PMID 38402536, 2024). "We showed that high infiltration of FOXP3+ T-cells might be an unfavorable prognostic factor for squamous cell lung cancer." (PMID 32933105, 2020). "Additionally, squamous cell lung cancer was characterized by a higher content of CD68+ macrophages (p = 0.0343) and FOXP3+ regulatory T cells (p = 0.0014), compared with adenocarcinomas." (PMID 32933105, 2020). "We also found that FOXP3 expression is not obvious with macrophage infiltration in a TME (R = 0.199, P = 9.63E−06), the same results were found in lung squamous cell carcinoma." (PMID 36550816, 2022).
meningioma (8 papers, 2015 to 2025). A generally slow growing tumor attached to the dura mater. "Despite this, there was a noted increase in FOXP3 expression in meningioma compared to the control tissues and VS tumours, and genes associated with T cell exhaustion in VS (TOX and TCF7)." (PMID 41437121, 2025). "Further, FOXP3+ cells (referring to regulatory T cells) were reported to be significantly increased in higher-grade meningiomas." (PMID 39273576, 2024). "Meanwhile, the expression of FoxP3 in WHO grade III meningioma (P < 0.001) was significantly higher than that of WHO grade I and WHO grade II meningioma, indicating the regulatory T (Treg) cells were rich in malignant meningioma." (PMID 37171006, 2023). "In particular, we note a significant decrease in CD4+ and CD8+ T lymphocytes, a decrease in PD-1+ lymphocytes and an increase in FOXP3+ Treg lymphocytes in WHO grade III meningioma." (PMID 25609200, 2015). "Interestingly, there was an increase in Foxp3+ cells in WHO grade II atypical meningioma and an even greater increase in WHO grade III anaplastic meningioma (p = 0.001)." (PMID 25609200, 2015). "In particular, grading in meningioma negatively correlates with the amount of CD4+, CD8+, and PD-1+ lymphocytes, along with increased numbers of Treg (FOXP3+) cells in the tumor." (PMID 35565385, 2022). "In anaplastic meningioma, there is a sharp decrease in the number of T cells, including the numbers of CD4+ and CD8+ T cells and cells expressing PD-1 and there is also an increase in the number of FOXP3 expressing immunoregulatory (Treg) cells." (PMID 25609200, 2015).
myasthenia gravis (8 papers, 2009 to 2024). Myasthenia gravis (MG) is a rare, clinically heterogeneous, autoimmune disorder of the neuromuscular junction characterized by fatigable weakness of voluntary muscles. "In addition, the conversion rate of CD4+CD25− T cells into CD4+CD25+FOXP3+ T cells was significantly higher in healthy individuals than in patients with Guillain-Barré syndrome or myasthenia gravis." (PMID 38822334, 2024). "Similarly, IFN-γ promoted a significant increase in the conversion of TCR-stimulated CD4+CD25− T cells to suppressive CD4+CD25+FOXP3+ T cells in patients with Guillain-Barré syndrome or myasthenia gravis." (PMID 38822334, 2024). "Disruption of the Foxp3 gene can cause early onset and fatal multi-organ inflammation and autoimmune diseases associated with skeletal muscle, including idiopathic inflammatory myopathy (IIM) and myasthenia gravis (MG), etc." (PMID 35869487, 2022). "The experimental results showed that in the animal model of MG (experimental autoimmune myasthenia gravis, EAMG), the number of CD4+CD25+ Tregs in CD4+ T spleen cells decreased and the expression of FoxP3 at mRNA level also decreased correspondingly." (PMID 26347149, 2015).